MCEMP1 (mast cell expressed membrane protein 1)
Diseases named in the same sentence as MCEMP1 in open-access papers (continued):
Sharing a sentence is not in itself a finding about the gene and the disease.
influenza (2 papers, 2020 to 2023). An acute viral infection of the respiratory tract, occurring in isolated cases, in epidemics, or in pandemics; it is caused by serologically different strains of viruses (influenzaviruses) designated A, B, and C, has a 3-day incubation period, and usually lasts for 3 to 10 days. "The expression of MCEMP1 reached the peak at day 3 post-vaccination either in NM65yrs (no more than 65 years) group or M65yrs (more than 65 years) group, with higher expression level identified in NM65yrs group at day 3 and 180 after influenza immunization." (PMID 33343577, 2020). "Third, the underlying mechanisms of MCEMP1 and SPARC genes contributing to the development of protective immunity after influenza vaccination should have been rigorously verified in multidimensions, especially the regulation of effector cytokines (CXCL 8/IL-8, Granzyme-B)." (PMID 33343577, 2020). "Furthermore, due to the insufficient research on potential biomarkers for the evaluation of influenza vaccine efficacy and safety, MCEMP1 and SPARC genes in our study may provide a good reference for further studies." (PMID 33343577, 2020). "The integrated functional analysis revealed MCEMP1 and SPARC as the hub genes during the development of safe and effective immunity related to influenza vaccines in the top age-related module and top gender-related module, respectively." (PMID 33343577, 2020). "This is probably the first study regarding the correlation of these two genes (MCEMP1, SPARC) with individual traits and immune responses in the development of effective immunity against influenza after QIVs inoculation." (PMID 33343577, 2020). "From these results, it can be concluded that the MCEMP1 and SPARC genes may have an effect on the development of protective humoral and cell immunity against influenza in the elderly." (PMID 33343577, 2020). "MCEMP1 showed a significantly higher expression in the NGR group than in the GR group, reaching the peak value at day 3 post-vaccination, highlighting the regulatory effect of dynamically expressed MCEMP1 on the safety and tolerability to the influenza vaccines." (PMID 33343577, 2020).
ischemic stroke (2 papers, 2021 to 2022). A stroke disorder caused by obstruction of blood flow to the brain, due to thrombotic (local blood clot formation) or embolic (due to a blood clot or other material traveling from another site) event. "C-type lectin domain family 4 member D (CLEC4D) and mast cell expressed membrane protein 1 (MCEMP1) are identified to be potential prognostic and diagnostic biomarkers for ischemic stroke." (PMID 34957234, 2021). "Furthermore, silencing MCEMP1 resulted in the upregulation of vascular endothelial growth factor (VEGF), while downregulation of Caspase3 led to the promotion of microvessel density (MVD) in rats with ischemic stroke." (PMID 35075378, 2022).
myocardial infarction (2 papers, 2023 to 2026). Gross necrosis of the myocardium, as a result of interruption of the blood supply to the area, as in coronary thrombosis. "Experimental validation in a murine model of myocardial infarction (MI) confirmed rapid upregulation of MCEMP1 after injury, closely mirroring the kinetics of neutrophil infiltration." (PMID 42187743, 2026).
type 1 diabetes (2 papers, 2024 to 2025). "We also found that the down-regulated pathways affected by MCEMP1 included graft versus host disease, intestinal immune network for IGA production, ribosome, spliceosome, and type I diabetes mellitus." (PMID 40599778, 2025). "CD163, MCEMP1 and RETN may jointly regulate complement and coagulation cascades, toll like receptor signaling pathway, graft versus host disease, type I diabetes mellitus." (PMID 40599778, 2025). "Using machine learning models to predict the potential mechanisms and targets of CD163, MCEMP1, and RETN proteins, CD163, MCEMP1 and RETN may jointly regulate complement and coagulation cascades, toll like receptor signaling pathway, graft versus host disease, type I diabetes mellitus." (PMID 40599778, 2025).
Aortic dissection (1 paper, 2022). Aortic dissection refers to a tear in the intimal layer of the aorta causing a separation between the intima and the medial layers of the aorta. "AGFG1, MCEMP1, IRAK3, KCNE1, and CLEC4D in module M37 were highly connected and strongly linked with AD, suggesting that these genes may help understand the pathogenesis of aortic dissection." (PMID 35178459, 2022).
cardioembolic stroke (1 paper, 2022). "However, the role of MCEMP1 in cardioembolic stroke (CS) and its underlying mechanisms remain poorly understood." (PMID 35075378, 2022).
chronic obstructive pulmonary disease (1 paper, 2024). A chronic and progressive lung disorder characterized by the loss of elasticity of the bronchial tree and the air sacs, destruction of the air sacs wall, thickening of the bronchial wall, and mucous accumulation in the bronchial tree. "To determine the cellular source of MCEMP1 in IPF lung tissues, we analyzed scRNA-Seq cells of the distal lung parenchyma from 32 IPF lungs, 18 chronic obstructive pulmonary disease (COPD), and 28 control donor lungs." (PMID 38189137, 2024).
heart failure (1 paper, 2023). Inability of the heart to pump blood at an adequate rate to meet tissue metabolic requirements. "Together, these data decipher the specific pro-inflammatory gene activation in DNMT3A mutant monocytes, demonstrating additional molecules, such as proteoglycan serglycin, phagolysosome genes, MCEMP1 and calreticulin, previously undescribed for CHIP-carrying patients with heart failure." (PMID 39196061, 2023).
monocytic leukemia (1 paper, 2024). "The MCEMP1 gene encodes a type II transmembrane protein, and its expression has been identified in monocytic leukemia cell lines (THP-1) and in lung mast cells." (PMID 38189137, 2024). "MCEMP1 is upregulated by transforming growth factor beta (TGFβ) at the mRNA and protein levels in monocytic leukemia THP-1 cells." (PMID 38189137, 2024).
neutropenia (1 paper, 2025). A decrease in the number of neutrophils found in the blood. "The neutrophil surface lipoprotein CD177 (fold change [FC] = 45.1), first described in neonatal neutropenia and the mast cell protein MCEMP1 (FC = 11.4), involved in mast cell maturation, were identified as the most strongly differential expressed genes in both cohorts." (PMID 40036168, 2025).
septic shock (1 paper, 2023). Shock caused by infection; frequently caused by gram negative bacteria, although some cases have been caused by other bacteria, viruses, fungi, and protozoa; characterized by fever, chills, tachycardia, tachypnea, and hypotension. "CD177, CLEC5A, CYSTM1, MCEMP1, MMP8, and RGL4 were identified as hub genes, which were of considerable value in the early diagnosis of septic shock patients." (PMID 37359526, 2023). "In addition, higher expression levels of CD177, CLEC5A, CYSTM1, MCEMP1, MMP8, and RGL4 messenger RNA (mRNA) were observed in peripheral blood mononuclear cells (PBMCs) isolated from septic shock patients than from healthy donors." (PMID 37359526, 2023).
type 2 diabetes mellitus (1 paper, 2025). A type of diabetes mellitus that is characterized by insulin resistance or desensitization and increased blood glucose levels. "We observed that MCEMP1 is mainly involved in the up-regulation pathway, including complement and coagulation cascades, lysosome, starch and sucrose metabolism, toll like receptor signaling pathway, type II diabetes mellitus." (PMID 40599778, 2025).
cancer (3 papers, 2020 to 2024). A tumor composed of atypical neoplastic, often pleomorphic cells that invade other tissues. "It is also known that small GTPases of the RHO/Rac family participate in TGFβ-induced EMT and cell motility in cancer, an effect that based on our results seems to be mediated in monocytes and macrophages in IPF, at least in part by MCEMP1." (PMID 38189137, 2024). "LRFN4, ADAMTS12, MCEMP1, HP and MUC15 are all cancer-related biomarkers, and all of them can also be used in judgment of cancer incidence in an independent manner." (PMID 32908454, 2020).
infection (2 papers, 2020 to 2023). The state of being infected such as from the introduction of a foreign agent such as serum, vaccine, antigenic substance or organism. "Future longitudinal studies that characterise the early transcriptomic events should provide more information on the kinetics of MCEMP1 and HLA-DRA gene and protein expression over the entire course of infection." (PMID 36801619, 2023).
tumor (2 papers, 2022). "MCEMP1, as a mast cell, is closely associated with the immune infiltration of tumor cells." (PMID 35378772, 2022). "And, abnormal expression of MCEMP1 in GC is correlated with tumor immune cell infiltration." (PMID 35378772, 2022). "In addition, Abnormal expression of MCEMP1 in GC is correlated with tumor immune cell infiltration." (PMID 35378772, 2022). "Using TOST we identified two equivalently changed genes (SPICE1 and MCEMP1) and one inverse changed gene (STAMBPL1) by comparing tumor tissue data set 1 with the PBMC data set." (PMID 36304274, 2022).
inflammation (1 paper, 2023). Aberrant reaction of the microcirculation characterized by movement of fluid and leukocytes from the blood into extravascular tissues. "Collectively, these findings indicate that MCEMP1 may have a crucial function in pulmonary inflammation." (PMID 37041174, 2023). "Furthermore, we performed mast cell engraftment into Mcemp1–/– mice for OVA-induced chronic lung inflammation." (PMID 37041174, 2023).
MCEMP1 also shares sentences with these, for which no sentence is quoted: rheumatoid arthritis (2 papers); viral infection (2); Airway obstruction (1); autoimmune disorders (1); cardiomyopathy (1); Crohn disease (1); dengue (1); diabetes (1); graft versus host disease (1); legionellosis (1); leishmaniasis (1); lung carcinoma (1); lymphopenia (1); multiple sclerosis (1); myocarditis (1); prion disease (1); systemic lupus erythematosus (1).